BMPR2 (bone morphogenetic protein receptor type 2)
Diseases named in the same sentence as BMPR2 in open-access papers (continued):
Sharing a sentence is not in itself a finding about the gene and the disease.
pulmonary arterial hypertension (continued). "Our findings show that analyses on the RNA level increase the rate of BMPR2 mutation detection, highlight the involvement of aberrant pre-mRNA splicing in the pathogenesis of pulmonary arterial hypertension and extend the mutational spectrum of the BMPR2 gene." (PMID 24621962, 2014). "In the same vein, patients with heritable pulmonary arterial hypertension, due to missense mutations in the BMPR2 gene, present earlier and with more severe disease than patients harbouring truncating mutations." (PMID 23820649, 2013). "SNPs in bone morphogenetic protein receptor 2 (BMPR2) is associated with familial and sporadic pulmonary hypertension, and acute chest syndrome in women with SCD is associated with a SNP in the endothelial nitric oxide synthase gene (NOS3)." (PMID 23762099, 2013). "For this reason there was considerable interest in the discovery that patients with a rare form of autosomal dominant, Heritable Pulmonary Arterial Hypertension (HPAH) carry mutations in the BMPR2 (bone morphogenetic protein receptor 2) gene." (PMID 24224048, 2013). "Mutations in the tail domain of BMPR2 are found in familial cases of pulmonary arterial hypertension." (PMID 24116187, 2013). "Beyond its developmental role, signaling through BMPR2 is associated with several adult diseases, including arthritis, pulmonary hypertension, atherosclerosis, diabetic nephropathy, renal fibrosis, and osteoporosis." (PMID 22348410, 2012). "Bmpr2 is modulated under hypoxic conditions and these knockout mice are more susceptible to hypoxic pulmonary hypertension." (PMID 21666745, 2011). "So far, genetic variants in the BMPR2 have been described to be responsible for the majority of cases of the autosomal hereditable pulmonary arterial hypertension." (PMID 21311592, 2011). "Autosomal dominant inheritance of germline mutations in the bone morphogenetic protein receptor type 2 (BMPR2) gene are a major risk factor for pulmonary arterial hypertension (PAH)." (PMID 19785764, 2009). "In individuals affected by familial forms of pulmonary arterial hypertension (PAHF) associated with loss-of-function mutations in bone morphogenetic protein receptor type II (BMPR2), a major genetic cause of PAHF, TNC overexpression is evident in pulmonary vascular lesions." (PMID 40981103, 2025). "Moreover, homozygous and heterozygous mutations in BMPR2 in rats lead to spontaneous pulmonary hypertension, as evidenced by pulmonary artery pressure, pulmonary vascular resistance, right ventricular hypertrophy, and decreased cardiac output." (PMID 40076974, 2025). "Gene mutations are the main genetic cause of pulmonary arterial hypertension.BMPR2 signaling is anti-inflammatory in vascular endothelium.Genetic factor involved in the development of COPD.Expression is decreased by exposure to cigarette smoke in lung tissue samples." (PMID 37483631, 2023). "Mutations in BMPR2 is the major genetic cause for pulmonary arterial hypertension (PAH)." (PMID 35504921, 2022). "Furthermore, even though BMPR2 is an autosomal gene, females with the mutations more commonly develop pulmonary hypertension than males." (PMID 34068984, 2021). "In addition, loss of the major type 2 receptor for BMP9, BMPR-2, promotes endothelial permeability and contributes to the development of pulmonary arterial hypertension." (PMID 33320799, 2021). "We describe two unrelated patients found to carry the same hitherto unreported pathogenic BMPR2 mutation; one of whom presented with typical pulmonary arterial hypertension, whereas the second patient presented with aggressive disease and characteristic clinical features of PVOD/PCH." (PMID 32547734, 2020). "BMPR2 is expressed in a number of cell types; however, this heterozygous mutation is of the greatest importance, particularly in the PA endothelium, because of its role in pulmonary hypertension." (PMID 32708482, 2020).
pulmonary arterial hypertension (continued). "In addition, BMPR2, the main genetic cause of pulmonary hypertension, is involved in embryonal development and in bone formation." (PMID 33095795, 2020). "This pulmonary hypertension phenotype in BMPR2-deficient mice is reversed by ANA." (PMID 30923189, 2019). "BMPR2 inactivating mutations cause pulmonary arterial hypertension." (PMID 31889906, 2019). "BMPR2 has been found to be implicated in diverse disease conditions, such as human osteosarcoma metastasis and pulmonary arterial hypertension, suggesting that dysregulation of BMPR2 might contribute to disease progression." (PMID 31889906, 2019). "The significance of the BMP9–ALK-1/BMPR2-mediated signal in endothelial cell is supported by the causal mutations identified in pulmonary arterial hypertension and hereditary hemorrhagic telangiectasia patients in the ACVRL1 and GDF2 genes, which encode ALK-1 and BMP9, respectively." (PMID 30272025, 2018). "Daily injections of BMP9 into a hereditary pulmonary arterial hypertension model mouse harboring a heterozygous R899X mutation in BMPR2 ameliorates the established pulmonary arterial hypertension phenotype, supporting a therapeutic potential of BMP9 for pulmonary arterial hypertension." (PMID 30272025, 2018). "As of 2017 there are 370 identified mutations in BMPR2 associated with pulmonary hypertension." (PMID 30149506, 2018). "Furthermore, patient-specific EC derived from iPSC have demonstrated a protective effect against pulmonary hypertension in familial pulmonary arterial hypertension with bone morphogenetic protein receptor type 2 (BMPR2) mutation." (PMID 28839272, 2017). "Moreover, attenuation of BMP signaling specifically in the endothelium by selective deletion of BMPR2 is found to be sufficient to cause pulmonary vascular remodeling and the spontaneous development of pulmonary hypertension in mice." (PMID 25187962, 2014). "Thus, in pulmonary arterial hypertension, a disease caused by mutations in the bone morphogenetic protein receptor type 2 (BMPR2) gene, the penetrance of the BMPR2 disease allele is dependent upon the level of expression of the wild-type BMPR2 allele." (PMID 23820649, 2013). "Pulmonary arterial hypertension (PAH) is characterized by excessive pulmonary vasoconstriction and vascular remodelling, with mutations in bone morphogenetic protein receptor type 2 (BMPR2) being the most common genetic alteration associated with the disease." (PMID 41948512, 2026). "We present 3 cases of epithelial neoplasms in 3 women with heritable pulmonary arterial hypertension (PAH) associated with mutations in the BMPR2 gene under advanced therapy, all diagnosed at an early age." (PMID 40923964, 2025). "A majority of familial Pulmonary arterial hypertension (PAH) patients, over 70%, and a significant proportion of idiopathic PAH patients, over 20%, possess heterozygous mutations that impair BMPR2 activity." (PMID 40136410, 2025). "SMURF1 levels are increased in pulmonary arterial hypertension (PAH), a disease caused by mutation of bone morphogenetic protein receptor-2 (BMPR2)." (PMID 40179885, 2025). "For example, mutations in BMPR2 (bone morphogenetic protein receptor type II) can cause pulmonary arterial hypertension (PAH)." (PMID 38543122, 2024). "Furthermore, a study showed that CCL5 deficiency could reverse hypoxia-induced pulmonary hypertension by restoring bone morphogenetic protein receptor 2 (BMPR2) signaling." (PMID 39119185, 2024). "BMPR2 has been demonstrated to be strongly associated with pulmonary arterial hypertension (PAH), a progressive disease characterized by elevated pressure in the pulmonary artery and right ventricle hypertrophy." (PMID 39142248, 2024). "IL-6 and TNF-α that are robustly high during COVID-19 have been linked to reduced BMPR2 expression and associated with severe disease and death in patients with pulmonary arterial hypertension (PAH)." (PMID 36634048, 2023).
pulmonary arterial hypertension (continued). "Loss of function mutations in the BMPR2 gene are involved in a large proportion of both familial and idiopathic cases of pulmonary arterial hypertension and genetic mutation of Bmpr2 in rats causes the spontaneous development of pulmonary and cardiac characteristics of pulmonary artery hypertension." (PMID 36625900, 2023). "In line with our studies implicating SCUBE1 in BMP signaling, it was shown that SCUBE1 is downregulated in pulmonary arterial hypertension (PAH) with BMPR2 mutation." (PMID 37237303, 2023). "Hyper-methylation of BMPR2 increases the risk of pulmonary arterial hypertension (PAH), while acetylation of H3K27 also increases the risk of PAH." (PMID 37900914, 2023). "In pulmonary arterial hypertension (PAH), BMPR2 loss-of-function mutations are involved in the pathogenesis of many patients, supporting the idea of a protective role of BMP activity." (PMID 36717825, 2023). "BMPR2 is a type II Transforming Growth Factor (TGF)-β family receptor that is fundamentally associated with pulmonary arterial hypertension (PAH) in humans." (PMID 35643319, 2022). "Loss-of-function or -expression mutations in BMPR2 result in pulmonary arterial hypertension (PAH), a disease of the pulmonary arteries with high morbidity and mortality." (PMID 34400635, 2021). "Mutations in the BMPR2 gene were the first genetic perturbations implicated in the pathophysiology of pulmonary arterial hypertension (PAH) and are still responsible for most cases of hereditary PAH (hPAH) to date." (PMID 32521690, 2020). "Since its association with familial pulmonary arterial hypertension (PAH) in 2000, Bone Morphogenetic Protein Receptor II (BMPR2) and its related signaling pathway have become recognized as a key regulator of pulmonary vascular homeostasis." (PMID 30149506, 2018). "Mutations in the gene encoding the bone morphogenetic protein receptor type II (BMPR2) are the commonest genetic cause of pulmonary arterial hypertension (PAH)." (PMID 26795434, 2016). "Pulmonary arterial hypertension (PAH) occurs more frequently in women with mutations in bone morphogenetic protein receptor type 2 (BMPR2) and dysfunctional BMPR2 signalling underpinning heritable PAH." (PMID 25765937, 2015). "Mutations of the BMPR2 gene have been implicated in the pathogenesis of pulmonary arterial hypertension (PAH) in human." (PMID 24586530, 2014). "Our study tested the hypothesis that a Th2 immune response in the lungs induced in response to a mild antigen would trigger or exacerbate the pulmonary hypertension phenotype in mice carrying a BMPR2 transgene that models a hypomorphic mutation found in a family of patients affected with PAH." (PMID 23383100, 2013). "Hypomorphic mutations in the bone morphogenic protein receptor (BMPR2) confer a much greater risk for developing pulmonary arterial hypertension (PAH)." (PMID 23383100, 2013). "Loss-of-function mutations in the bone morphogenetic protein receptor type 2 (BMPR2) gene have been identified in patients with heritable pulmonary arterial hypertension (PAH); however, disease penetrance is low, suggesting additional factors play a role." (PMID 22427841, 2012). "In humans, pulmonary arterial hypertension (PAH) has a female predominance, and is associated with decreased BMPR2 expression." (PMID 22348410, 2012). "While BMPR2 mutation strongly predisposes to pulmonary arterial hypertension (PAH), only 20% of mutation carriers develop clinical disease." (PMID 18823550, 2008). "Together with HHT, also pulmonary arterial hypertension (PAH) arises following perturbation of TGF-β signal and, in particular, due to BMPR2 gene mutation, encoding for the BMP type 2 receptor." (PMID 40282211, 2025). "Pulmonary arterial hypertension (PAH) is a rare disease that can be caused by pathogenic variants, most frequently in the bone Morphogenetic Protein Receptor Type 2 (BMPR2) gene." (PMID 40661831, 2025).
pulmonary arterial hypertension (continued). "Animal studies suggest a significant correlation between the expression of the pulmonary arterial hypertension-related gene BMPR2 and the hypoxia-sensing gene HIF1A during short-term high-altitude acclimatization." (PMID 41404581, 2025). "In an affected pulmonary arterial smooth muscle cell in familial pulmonary arterial hypertension (PAH), the genetic mutation of BMPR2 disrupts BMP signaling, which results in an imbalance between apoptosis and cell proliferation, thereby causing vascular remodeling." (PMID 40437633, 2025). "BMPR2 mutations cause heritable pulmonary arterial hypertension (PAH) and may also influence epithelial carcinogenesis." (PMID 40923964, 2025). "Reduction of BMPR2 mRNA expression in peripheral blood of pulmonary arterial hypertension patients: a marker for disease severity?" (PMID 38771375, 2024). "BMPR2 acts as a gatekeeper to protect endothelial cells from increased TGFβ responses, as highlighted by its deregulation in diseases such as pulmonary arterial hypertension (PH)." (PMID 38674024, 2024). "Functionally active BMPR2 signaling promotes pulmonary endothelial cell survival and targeted delivery of BMPR2 attenuates pulmonary hypertension in rats." (PMID 36625900, 2023). "In the SuHx animal model, which exhibits a more severe form of pulmonary hypertension, there is an activation of MMP9-mediated cleavage of COMP and subsequently loss of its stabilization of BMPR2." (PMID 38001814, 2023). "BMPR2−/− mice consistently exhibit severe pulmonary hypertension, skeletal disorders, and embryonic lethality." (PMID 36675162, 2023). "Our method yields penetrance estimates which align with those obtained via existing approaches in the Parkinson’s disease LRRK2 gene and pulmonary arterial hypertension BMPR2 gene case studies." (PMID 36522764, 2022). "Previously, we have shown that monocrotaline-induced pulmonary hypertension was attenuated in IKBM mice by restoring BMPR2 (in part) indicated NF-κB- mediated regulation." (PMID 35083615, 2022). "Notably, mutations in the BMPR2 gene are profoundly associated with pulmonary arterial hypertension (PAH), a highly morbid disorder characterized by vascular remodeling with progressive obliteration of the lung microvascular system." (PMID 35643319, 2022). "It is now well established that around 70–80% of heritable pulmonary arterial hypertension (PAH) and 10–20% of idiopathic PAH cases are related with genetic variants in bone morphogenetic protein receptor type-2 (BMPR2)." (PMID 35811711, 2022). "The expression of receptors associated with pulmonary hypertension and RV remodeling such as receptor (HTR1B), BMPR2 and endoglin were not affected by MA." (PMID 33789156, 2021). "For example, iPSC-ECs were generated to study the BMPR2 (bone morphogenetic protein receptor type II) mutation that causes pulmonary arterial hypertension (PAH) and PAH-specific iPSC-ECs exhibited decreased tube formation, LDL uptake, adhesion, migration, and survival." (PMID 33659279, 2021). "Here the authors show that the dysregulation of the activin A-bone morphogenetic protein receptor type 2 link in the endothelium is involved in the progression of pulmonary hypertension." (PMID 33741934, 2021). "Increased lipid deposition has been observed in cardiomyocytes in the rightventricle of pulmonary hypertensive BMPR2 mutant mice." (PMID 32999709, 2020). "This likely results from damage of the endothelial cells and apoptosis by BMPR2 signaling disregulation, which contributes to inflammation and thrombosis in pulmonary hypertension." (PMID 32708482, 2020). "In the pathogenesis of pulmonary hypertension, the main abnormalities are connected with mutations altering the properties of ALK1 and ALK5, BMPR2 and endoglin receptors, and SMAD8 signalling proteins (they are responsible for inhibiting signalling by R-SMAD)." (PMID 32566097, 2020).
pulmonary arterial hypertension (continued). "BMP9 is shown to reinstate BMP receptor type-II (BMPR2) levels and thereby mitigate hemodynamic and vascular abnormalities in several animal models of pulmonary hypertension (PH)." (PMID 32813135, 2020). "While pathogenic variants in the bone morphogenetic protein receptor 2 gene (BMPR2) and related pathway genes have been described in patients with pulmonary arterial hypertension (PAH) only two studies reported CTEPH patients with pathogenic variants in the BMPR2 gene." (PMID 32397294, 2020). "Rare genetic variation, primarily in genes associated with transforming growth factor-β family members, including BMPR2, but also in the transcription factor SOX17, is known to cause pulmonary arterial hypertension." (PMID 30527956, 2019). "The first demonstration of BMPR2 gene therapy was conducted successfully in 2007 in the chronic hypoxia rat model of pulmonary hypertension (PH), yet the clinical translation of a gene therapy approach is challenging." (PMID 30149506, 2018). "Immune reconstitution of exogenous regulatory T cells reverses pulmonary hypertension with a significant increase in whole-lung BMPR2 expression." (PMID 30149506, 2018). "For example, in BMPR2 mutant mice—with deletion of BMPR2 in only the vascular endothelium—treatment resulted in protection against pulmonary hypertension progression." (PMID 30081463, 2018). "In heritable pulmonary arterial hypertension, the ratio between two alternatively spliced BMPR2 transcripts, with a single exon difference, results in different disease penetrance." (PMID 27324164, 2016). "Furthermore, patients with hereditary pulmonary arterial hypertension (PAH) exhibit endothelial cell dysfunction and vascular leakage that have been linked to heterozygous BMPR2 mutations." (PMID 26598555, 2016). "In this study we assessed if EIF2AK4 mutations occur also in a family with autosomal dominantly inherited pulmonary arterial hypertension (HPAH) and incomplete penetrance of bone morphogenic protein receptor 2 (BMPR2) mutations." (PMID 27809840, 2016). "Mutations in the type 2 receptor for the bone morphogenic protein (BMP) pathway, BMPR2, are responsible for the majority of the heritable form of pulmonary arterial hypertension, and sizable minority of the idiopathic form." (PMID 24713633, 2014). "Classic biomarkers of pulmonary arterial hypertension such as the downregulated expression of lung BMPR2, Kv1.5, Kv2.1, upregulated survivin, endothelial dysfunction and hyperresponsiveness to 5-HT were unaffected by quercetin." (PMID 25460361, 2014). "Mutations of BMPR2 and other TGF-β superfamily genes have been reported in pulmonary arterial hypertension (PAH)." (PMID 24936512, 2014). "BMPR2 deletion in homozygous mice (BMPR2−/−) results in embryonic lethality, heterozygous BMPR2+/− mice are phenotypically normal and can develop pulmonary hypertension upon inflammatory insults." (PMID 24586530, 2014). "BMPR2 is implicated in the development of pulmonary arterial hypertension (PAH)." (PMID 24116187, 2013). "Our findings support the idea that there is a molecular connection between a hypomorphic BMPR2, asthma-like responses and pulmonary hypertension as previously suggested by studies performed in pediatric pulmonary hypertension patients." (PMID 23383100, 2013). "Using the BMPR2R899X mouse, we tested the idea that the Th2 immune response to inhaled antigen would exacerbate the pulmonary hypertension phenotype in mice that express the hypomorphic BMPR2 transgene." (PMID 23383100, 2013). "The current studies were designed to test the idea that Th2 responses to a mild antigen together with the expression of a hypomorphic BMPR2 gene would trigger pulmonary hypertension." (PMID 23383100, 2013). "Dr. Zhang and colleagues showed that monocrotaline induced inflammation was one of the requisite secondary triggers of pulmonary hypertension in mice that have a heterozygous BMPR2 deletion." (PMID 23383100, 2013).